PUS7 (pseudouridine synthase 7)
Description:
Pseudouridylate synthase that catalyzes pseudouridylation of RNAs. Acts as a regulator of protein synthesis in embryonic stem cells by mediating pseudouridylation of RNA fragments derived from tRNAs (tRFs): pseudouridylated tRFs inhibit translation by targeting the translation initiation complex. Also catalyzes pseudouridylation of mRNAs: mediates pseudouridylation of mRNAs with the consensus sequence 5'-UGUAG-3'. Acts as a regulator of pre-mRNA splicing by mediating pseudouridylation of pre-mRNAs at locations associated with alternatively spliced regions. Pseudouridylation of pre-mRNAs near splice sites directly regulates mRNA splicing and mRNA 3'-end processing. In addition to mRNAs and tRNAs, binds other types of RNAs, such as snRNAs, Y RNAs and vault RNAs, suggesting that it can catalyze pseudouridylation of many RNA types.
Synonyms: FLJ20485; IDDABS
Tractability: PROTAC: ubiquitination databases record sites on it; its protein half-life has been measured.
Gene: Protein-coding gene on chromosome 7 (105,439,661 to 105,522,272, reverse strand). Ensembl gene ENSG00000091127.
Subcellular location: Nucleus
Subcellular location (Human Protein Atlas): Nucleoplasm
Pathways (Reactome):
Metabolism of RNA: tRNA modification in the nucleus and cytosol
Gene Ontology:
Molecular function: enzyme binding; pseudouridine synthase activity; RNA binding; tRNA pseudouridine synthase activity; tRNA pseudouridine(13) synthase activity
Biological process: mRNA pseudouridine synthesis; negative regulation of translation; regulation of hematopoietic stem cell differentiation; regulation of mesoderm development; tRNA pseudouridine synthesis; pseudouridine synthesis; RNA modification
Cellular component: nucleus
Genetic constraint (gnomAD): Loss-of-function variants: 33 observed, 60.71 expected, observed/expected ratio (o/e) 0.54, 90% interval 0.41 to 0.73. The upper end of that interval is the gene's LOEUF score, 0.73, which puts it in group 2 of 6, group 1 being the genes least tolerant of losing a copy. Missense variants: 571 observed, 651.36 expected, observed/expected ratio (o/e) 0.88, 90% interval 0.82 to 0.94. Synonymous variants: 223 observed, 227.79 expected, observed/expected ratio (o/e) 0.98, 90% interval 0.88 to 1.09.
Homologues: Orthologues: chimpanzee PUS7 (100% identical), chimpanzee PUS7 (99% identical), macaque PUS7 (98% identical), dog PUS7 (92% identical), rabbit PUS7 (92% identical), guinea pig PUS7 (91% identical), pig PUS7 (90% identical), rat Pus7 (89% identical), mouse Pus7 (89% identical), tropical clawed frog pus7 (76% identical), zebrafish pus7 (65% identical), Drosophila melanogaster Pus7 (35% identical). Paralogues in human: PUS7L (25% identical).
Diseases named in the same sentence as PUS7 in open-access papers:
PUS7 is named in the same sentence as 49 diseases in open-access papers, as found by Europe PMC text mining. Sharing a sentence is not in itself a finding about the gene and the disease. The quoted sentences say what the papers report.
glioblastoma (22 papers, 2022 to 2026). The most malignant astrocytic tumor (WHO grade IV). "Among them, PUS7—the sole member of the TruD family has been linked to tumour progression in glioblastoma, colorectal cancer, and gastric cancer, with both oncogenic and tumour‐suppressive roles reported depending on the cancer type." (PMID 41496500, 2026). "PUS7 has been implicated in promoting the tumourigenesis of glioblastoma stem cells via PUS7‐dependent tRNA modification." (PMID 39175405, 2024). "Aberrant expressions or activity of PUS7 have been linked to a variety of pathological conditions, including cancers such as colon cancer, glioblastoma, pancreatic cancer, and neuroblastoma, as well as potential roles in neurodevelopmental disorders and immune regulation." (PMID 40940790, 2025). "This modification by PUS7 is associated with worse survival outcomes in patients with glioblastoma." (PMID 40176140, 2025). "Recently, it has been reported that PUS7 can serve as an underlying biomarker for glioma in a neurological tumor, glioblastoma, and up-regulated PUS7 increased Ψ modification in tRNA and decreased TYK2 translation can promote tumor progression through the interferon-STAT1 pathway." (PMID 37420297, 2023). "In glioblastoma, PUS7 targets the tRNA for pseudouridylation, affecting the interferon-STAT1 pathway and cell growth by reducing Tyk2 translation." (PMID 41554761, 2026). "Limited research currently exists on the connection between PUS7 and solid tumors except for glioblastoma and colorectal cancer." (PMID 41554761, 2026). "Recent studies have made promising advances in targeting PUS7 to suppress tRNA pseudouridylation and inhibit glioblastoma tumourigenesis." (PMID 39834094, 2025). "These inhibitors present potential as therapeutic candidates targeting PUS7 in glioblastoma and potentially other cancers." (PMID 39834094, 2025). "Among them, C17 exhibited a stronger and dose-dependent inhibitory effect on patient-derived glioblastoma stem cells in a PUS7-dependent manner in vitro and that it preferentially targets glioblastoma stem cells compared to neural stem cells." (PMID 40940790, 2025). "In the context of pseudouridylation, the most abundant RNA modification in glioblastoma, PUS7 has been shown to reduce CXCL10 expression." (PMID 40176140, 2025). "In immunodeficient NOD scid gamma (NSG) mice, transplantation of glioblastoma stem cells with knockdown of PUS7 significantly inhibited tumor progression and prolonged survival compared to controls." (PMID 40940790, 2025). "In glioblastoma, elevated PUS7 expression correlates with poor prognosis, and PUS7 knockout in glioblastoma stem cells (GSCs) significantly reduces their self‐renewal capacity and frequency." (PMID 39834094, 2025). "PUS7 has been identified as a targetable epitranscriptomic regulator of glioblastoma growth, and its high expression is correlated with lower survival rates in tumor patients." (PMID 41446042, 2025). "The use of chemical inhibitors to disrupt PUS7 function presents a promising avenue for halting tumor advancement and prolonging survival in glioblastoma models, presenting a novel approach to combatting this aggressive form of brain cancer." (PMID 39061374, 2024). "Another predicted small molecule demonstrates efficacy in suppressing glioblastoma tumorigenesis by reducing PUS7 activity in glioblastoma xenograft mouse models." (PMID 38476632, 2024). "Elevated expression and catalytic activity of pseudouridine synthase 7 (PUS7) have been observed in glioblastomas, correlating with unfavorable patient prognoses." (PMID 39061374, 2024). "For example, PUS7 is highly expressed in glioblastoma, where it promotes tumorigenesis by regulating codon-specific translation of key glioblastoma stem cell factors through tRNA pseudouridylation." (PMID 39247811, 2024). "PUS7 modifies tRNAs in glioblastoma, reduces TYK2 translation and downregulates proliferation by limiting the interferon‒Stat1 pathway." (PMID 38572667, 2024).
glioblastoma (continued). "The significant involvement of PUS7 in promoting tumor growth in glioblastoma stem cells (GSCs) underscores its potential as a crucial therapeutic target." (PMID 39061374, 2024). "Recent findings demonstrated that suppressing PUS7 drastically reduced the self-renewal of glioblastoma stem cells (GSCs), leading to tumor progression inhibition in mice." (PMID 38476632, 2024). "For instance, PUS7's involvement in promoting glioblastoma stem cell tumourigenesis has been established through PUS7‐dependent tRNA modification." (PMID 39175405, 2024). "PUS7 plays a role in controlling the tumorigenesis of glioblastoma stem cells (GSCs) by regulating codon-specific translation control of key GSC regulators through tRNA pseudouridylation." (PMID 39737343, 2024). "DKC1 and PUS7 have been proven to be oncogenes in many cancers, such as colorectal cancer, glioblastoma, prostate cancer, breast cancer and lung adenocarcinoma." (PMID 37925171, 2023). "It is similar to the findings of PUS7 in other malignancies, which have been reported to affect glioblastoma growth and tumorigenesis by regulating TYK2 translation through tRNA-dependent pseudouridylation." (PMID 37420297, 2023). "In this context, inhibitors targeting different RNA modifications, such as FTO or PUS7 inhibitors, have demonstrated promising results in independently suppressing glioblastoma and reducing self-renewal." (PMID 37928731, 2023). "In cancer research, PUS7 has received a lot of attention and has been reported to play a crucial role in the progression of leukemia, glioblastoma and colorectal cancer." (PMID 37596681, 2023). "High expression of pseudouridine synthase 7 (PUS7) prognosticates the poor outcome of individuals with glioblastoma and inhibition of PUS7-mediated pseudouridine modification restrained the glioblastoma stem cell (GSC) tumorigenesis." (PMID 36457503, 2022). "Elevated PUS7 expression has been reported in multiple types of cancer, including pancreatic cancer, ovarian cancer, breast cancer, neuroblastoma, non-small cell lung cancer, hepatocellular carcinoma, colorectal cancer, and glioblastoma." (PMID 40940790, 2025). "Methyltransferase PUS7 is a targeted external transcriptome regulator of glioblastoma growth." (PMID 38572667, 2024). "Besides, PUS7 was also proved to be upregulated in colorectal cancer, and glioblastoma stem cells and correlated with the malignancy." (PMID 37925171, 2023). "The depletion of PUS7 also significantly reduced the population of CRC stem cells marked by CD133, showing that PUS7 plays a key role in the self-renewal of CRC stem cells, which aligns well with previous studies on glioblastoma (GBM) stem cells." (PMID 41168165, 2025). "In glioblastoma multiforme (GBM), elevated expression of PUS7 has been observed." (PMID 38476632, 2024). "For instance, PUS7 facilitates pseudouridylation at Ψ50 in several tRNA isoforms, involving tRNA‐Arg‐CCG, tRNA‐Gln‐CTG, tRNA‐Asp‐GTC, tRNA‐Glu‐CTC, and tRNA‐Tyr‐GTA, enhancing the translation of tyrosine kinase 2 (TYK2) by mediating the transport of specific amino acids in glioblastoma." (PMID 39834094, 2025).
colorectal cancer (13 papers, 2021 to 2026). A primary or metastatic malignant neoplasm that affects the colon or rectum. "Nevertheless, the role and the underlying molecular mechanisms of PUS7 in solid tumours, such as colorectal cancer (CRC), remain unexplored." (PMID 33990203, 2021). "In colorectal cancer, PUS7 regulates the PI3K/Akt/mTOR signaling cascade, where PUS7 knockdown in colorectal cancer cells led to reduced phosphorylation of PI3K, Akt, and mTOR, while PUS7 overexpression enhanced their phosphorylation in colon cancer cells." (PMID 40940790, 2025). "In our study, we used bisulfite-induced deletion sequencing (BID-seq), to profile Ψ landscape on nuclear RNA and identified 7SK as one of the PUS7 substrates in colorectal cancer (CRC) cells." (PMID 41168165, 2025). "Here, the authors show that the PUS7-mediated pseudouridylation of 7SK RNA regulates Pol II elongation and affects colorectal cancer cell survival and response to 5-FU treatment." (PMID 41168165, 2025). "Colorectal cancer cells with either PUS7 knockdown or PUS7 overexpression were injected into the tail veins of BALB/c nude mice." (PMID 40940790, 2025). "The role of PUS7 in metastasis was investigated using an in vivo colorectal cancer metastasis model." (PMID 40940790, 2025). "PUS7 also facilitates the metastasis of colorectal cancer cells by upregulating LASP1 (LIM and SH3 protein 1), independent of PUS7's catalytic activity." (PMID 39175405, 2024). "Several researchers have reported the overexpression of PUS7 in colorectal cancer (CRC) tissues, which is correlated with advanced clinical stages and reduced overall survival rates." (PMID 39737343, 2024). "Recent studies have shown that HSP90 can promote the metastasis of colorectal cancer cells by regulating LASP1 abundance in a PUS7-dependent manner." (PMID 36203415, 2022). "Additionally, gain-of-function studies revealed that PUS7 overexpression promotes migration and invasion of colorectal cancer cells through upregulation of LASP1." (PMID 40940790, 2025). "Additionally, in colorectal cancer, PUS7 exerts oncogenic effects by interacting with Sirtuin 1 (SIRT1) and activating the Wnt/β-catenin signaling pathway." (PMID 40940790, 2025). "For instance, PUS7 promotes colorectal cancer cell metastasis by regulating LASP115." (PMID 39247811, 2024). "Similarly, in colorectal cancer, PUS7 knockdown suppressed tumorigenicity in vivo." (PMID 40940790, 2025). "In colorectal cancer, PUS7 facilitates cancer cell migration through the HSP90/PUS7/LASP1 pathway, enhances proliferation via SIRT1 activating the Wnt/β-catenin pathway, and stimulates proliferation and invasion through the PI3K/AKT/mTOR signaling pathway." (PMID 41554761, 2026). "In colorectal cancer (CRC) cells, the Ψ level of 7SK can be modulated by PUS7, or by site-specifically targeted pseudouridylation through dCas13b-guided system." (PMID 41168165, 2025). "In colorectal cancer, pseudouridine synthase PUS7 promotes metastasis through a non-enzymatic pathway by regulating LASP115." (PMID 39247811, 2024). "Previous literature has reported that pseudouridine synthase PUS7, through a non-enzymatic pathway, interacts with LASP1, stabilizing the latter and promoting colorectal cancer cell metastasis." (PMID 39247811, 2024). "PUS7 silencing effectively repressed metastasis in colorectal cancer (CRC) cells, whereas PUS7 upregulation promoted metastasis independent of the catalytic activity of PUS7." (PMID 39737343, 2024). "However, another study suggests that PUS7 also can activate the Wnt/β-catenin pathway by acting on Sirtuin 1 and PI3K/AKT/mTOR signaling pathway, indicating that PUS7 may simultaneously act on multiple downstream targets and promote colorectal cancer progression." (PMID 37420297, 2023).
myelodysplastic syndrome (10 papers, 2020 to 2025). A clonal hematopoietic disorder characterized by dysplasia and ineffective hematopoiesis in one or more of the hematopoietic cell lines. "Deletion of PUS7 has been linked to abnormalities on chromosome 7 in myelodysplastic syndrome (MDS), which are clonal disorders of hematopoietic stem cells and progenitor cells (HSPCs) associated with a high risk of AML." (PMID 39737343, 2024). "Surprisingly, PUS7 is encoded in a region known to be deleted in myelodysplastic syndromes (MDS)—rare disorders of blood cell progenitor regulation that cause diverse symptoms and a high risk of leukemic transformation." (PMID 32890397, 2020). "Significantly, we found that PUS7 was frequently altered in myelodysplastic syndrome (MDS), a collection of clonal haematological disorders associated with HSPC dysfunction and high risk of leukaemia transformation." (PMID 32116113, 2020). "Recent studies implicate PUS7 in myelodysplastic syndromes (MDS), where chromosome 7 deletions are frequent." (PMID 40973767, 2025). "Nevertheless, the clues for a direct function of pseudouridine modification and for the various PUS enzymes in carcinogenesis have not been obtained, despite a recent study indicating a potential role for PUS7 in myelodysplastic syndromes." (PMID 37315299, 2023). "Notably, PUS7 levels were also found reduced in myelodysplastic syndromes (MDS), hematological disorders that may progress to acute myeloid leukemia (AML)." (PMID 33946178, 2021). "PUS7 recognizes UGUAR-like sequences and helps maintain RNA structural integrity, and its deletion is closely linked to transcriptional instability in myelodysplastic syndrome (MDS)." (PMID 41446042, 2025). "For instance, PUS7-mediated ψ activates certain tRNAs to control protein synthesis and influence stem cell differentiation, and dysregulation of this process may lead to myelodysplastic syndrome (MDS) worsening into acute myeloid leukemia (AML)." (PMID 37420297, 2023).
glioma (8 papers, 2021 to 2025). A benign or malignant brain and spinal cord tumor that arises from glial cells (astrocytes, oligodendrocytes, ependymal cells). "Likewise, a Ψ regulator, pseudouridine synthase 7 (PUS7), is highly expressed in glioma tissue, associated with poor survival, and PUS7 inhibitors could suppress tumour growth in mice." (PMID 36831575, 2023). "Recently, some studies have reported that PUS7 can be considered a possible biomarker for ovarian cancer diagnosis and as a prognostic predictor for glioma." (PMID 37420297, 2023). "Six Ψ synthase genes were associated with the prognosis, of which the expression of PUS1, PUS7, RPUSD1 and RPUSD3 was positively associated with the malignancy of glioma (HR > 1), and TRUB1 was negatively associated with the malignant grade (HR < 1)." (PMID 35118063, 2021). "Similarly, PUS7 knockout in glioma stem cells (GSCs) increases the expression of interferon-stimulated genes and inhibits GSC growth." (PMID 40260225, 2025). "Additionally, PUS7 is also reported to be a potential biomarker for glioma." (PMID 34827123, 2021). "The results showed that PUS1, PUS7, and DKC1 were significantly correlated with the prognosis of gliomas in different subgroups." (PMID 35118063, 2021).
ovarian carcinoma (6 papers, 2021 to 2024). A malignant neoplasm originating from the surface ovarian epithelium. "In a study on ovarian cancer, a pseudouridine synthase, PUS7, was considered a potential diagnostic marker for ovarian cancer." (PMID 36894952, 2023). "In conclusion, the findings of the present study point towards the potential of PUS7 as the diagnostic marker and therapeutic target for ovarian cancer." (PMID 34827123, 2021). "Collectively, the findings of the present study point towards the potential of PUS7 as a diagnostic marker and therapeutic target for ovarian cancer." (PMID 34827123, 2021). "For example, the bioinformatic data analysis found that PUS7 can be considered a potential biomolecule for ovarian cancer." (PMID 37420297, 2023). "In conclusion, the findings of the present study revealed PUS7 as a novel and prospective biomarker at the RNA and protein levels for ovarian cancer." (PMID 34827123, 2021). "In this study, we investigated dysregulated RMGs in ovarian cancer and identified PUS7 as a novel potential biomarker for the diagnosis of OV." (PMID 34827123, 2021). "In addition, some studies have also found that PUS7 is highly expressed in human ovarian cancer tissues." (PMID 38343637, 2024). "The top eight pathways in which PUS7 participates are DNA replication, the cell cycle, mismatch repair, spliceosomes, homologous recombination, RNA polymerase, aminoacyl tRNA biosynthesis, and one carbon pool by folate in ovarian cancer." (PMID 34827123, 2021). "Through the analysis of gene pathway data, it is considered that PUS7 may interact with NOC3L and PUS1 to promote the proliferation of ovarian cancer by regulating DNA replication and cell cycle." (PMID 38343637, 2024). "Further analysis indicated that PUS7 may interact with NOC3L and PUS1 to regulate ovarian cancer proliferation via modulation of DNA replication and the cell cycle." (PMID 34827123, 2021).